GRIN3A (glutamate ionotropic receptor NMDA type subunit 3A)
Description:
Component of a non-conventional N-methyl-D-aspartate (NMDA) receptors (NMDARs) that function as heterotetrameric, ligand-gated cation channels with low calcium permeability and low voltage-dependent block by Mg(2+) (By similarity). During the development of neural circuits, participates in the synaptic refinement period, restricting spine maturation and growth (By similarity). Forms glutamatergic receptor complexes with GluN1 and GluN2 subunits which are activated by glycine binding to the GluN1 and GluN3 subunits and L-glutamate binding to GluN2 subunits (By similarity). Forms excitatory glycinergic receptor complexes with GluN1 alone which are activated by glycine binding to the GluN1 and GluN3 subunits. GluN3A subunit also binds D-serine (By similarity). Each GluN3 subunit confers differential attributes to channel properties, including activation, deactivation and desensitization kinetics, pH sensitivity, Ca2(+) permeability, and binding to allosteric modulators (By similarity). By competing with GIT1 interaction with ARHGEF7/beta-PIX, may reduce GIT1/ARHGEF7-regulated local activation of RAC1, hence affecting signaling and limiting the maturation and growth of inactive synapses (By similarity).
Synonyms: GluN3A; NMDAR3A; NR3A; NMDAR-L
Tractability: Small molecule: an approved drug acts on it; a structure with a bound ligand is known; a high-quality ligand is known; it belongs to a druggable protein family. Antibody: UniProt places it where antibodies can reach, with medium confidence; UniProt predicts a signal peptide or a membrane-spanning region; its Gene Ontology location is reachable by antibodies, with medium confidence. PROTAC: a small molecule that binds it is known. Other modalities: a drug acting on it is in phase 2 or 3 trials.
Target class: Ion channel; Ionotropic glutamate receptor; Ligand-gated ion channel; NMDA receptor
Safety:
Unwanted effects reported when the protein is acted on. In parentheses: how it was acted on, where the effect was seen, and who reports it.
ataxia (inhibition, acute dosing; central nervous system, cardiovascular; source: Lynch et al. (2017))
convulsions (activation, acute dosing; central nervous system, cardiovascular; source: Lynch et al. (2017))
decreased convulsions (inhibition, acute dosing; central nervous system, cardiovascular; source: Lynch et al. (2017))
decreased memory (inhibition, acute dosing; central nervous system, cardiovascular; source: Lynch et al. (2017))
decreased pain (inhibition, acute dosing; central nervous system, cardiovascular; source: Lynch et al. (2017))
dizziness (inhibition, acute dosing; central nervous system, cardiovascular; source: Lynch et al. (2017))
drug abuse/dependence (inhibition, acute dosing; central nervous system, cardiovascular; source: Lynch et al. (2017))
impaired social interactions (inhibition, chronic dosing; central nervous system, cardiovascular; source: Lynch et al. (2017))
increased blood pressure (inhibition, acute dosing and activation, acute dosing; central nervous system, cardiovascular; source: Lynch et al. (2017))
increased heart rate (inhibition, acute dosing; central nervous system, cardiovascular; source: Lynch et al. (2017))
increased locomotor activity (inhibition, acute dosing; central nervous system, cardiovascular; source: Lynch et al. (2017))
increased then decreased heart rate (activation, acute dosing; central nervous system, cardiovascular; source: Lynch et al. (2017))
neurodegeneration (inhibition, chronic dosing; central nervous system, cardiovascular; source: Lynch et al. (2017))
neurotoxicity (inhibition, acute dosing; central nervous system, cardiovascular; source: Lynch et al. (2017))
pain (activation, acute dosing; central nervous system, cardiovascular; source: Lynch et al. (2017))
psychosis (inhibition, chronic or acute dosing; central nervous system, cardiovascular; source: Lynch et al. (2017))
stereotypy (inhibition, chronic dosing; central nervous system, cardiovascular; source: Lynch et al. (2017))
Gene: Protein-coding gene on chromosome 9 (101,569,352 to 101,738,647, reverse strand). Ensembl gene ENSG00000198785.
Subcellular location: Cell membrane; Postsynaptic cell membrane; Postsynaptic density
Pathways (Reactome):
Neuronal System: Assembly and cell surface presentation of NMDA receptors
Gene Ontology:
Molecular function: glycine binding; identical protein binding; NMDA glutamate receptor activity; protein binding; glutamate receptor activity; glycine-gated cation channel activity; protein phosphatase 2A binding; serine binding; transmitter-gated monoatomic ion channel activity; transmitter-gated monoatomic ion channel activity involved in regulation of postsynaptic membrane potential; calcium channel activity; ligand-gated monoatomic ion channel activity; monoatomic ion channel activity; signaling receptor activity
Biological process: response to ethanol; calcium ion transport; ionotropic glutamate receptor signaling pathway; modulation of chemical synaptic transmission; monoatomic cation transmembrane transport; negative regulation of dendritic spine development; regulation of synaptic plasticity; synaptic transmission, glutamatergic; brain development; calcium ion transmembrane transport; hippocampus development; hypothalamus development; mesencephalic trigeminal nucleus development; monoatomic ion transport; negative regulation of dendritic spine maintenance; presynaptic modulation of chemical synaptic transmission; regulation of postsynaptic membrane potential; trigeminal motor nucleus development
Cellular component: membrane; neuron projection; neuronal cell body; neurotransmitter receptor complex; NMDA selective glutamate receptor complex; synapse; endoplasmic reticulum membrane; plasma membrane; postsynaptic density; postsynaptic density membrane; postsynaptic membrane; cell surface; cytoplasm; glutamatergic synapse; organelle; presynapse; protein-containing complex; synaptic membrane
Genetic constraint (gnomAD): Loss-of-function variants: 43 observed, 85.6 expected, observed/expected ratio (o/e) 0.5, 90% interval 0.39 to 0.65. The upper end of that interval is the gene's LOEUF score, 0.65, which puts it in group 2 of 6, group 1 being the genes least tolerant of losing a copy. Missense variants: 1,299 observed, 1,382.6 expected, observed/expected ratio (o/e) 0.94, 90% interval 0.9 to 0.98. Synonymous variants: 515 observed, 540.79 expected, observed/expected ratio (o/e) 0.95, 90% interval 0.88 to 1.02.
Homologues: Orthologues: chimpanzee GRIN3A (99% identical), macaque GRIN3A (98% identical), dog GRIN3A (95% identical), rabbit GRIN3A (95% identical), mouse Grin3a (93% identical), pig GRIN3A (93% identical), guinea pig GRIN3A (93% identical), rat Grin3a (93% identical), tropical clawed frog grin3a (77% identical), Caenorhabditis elegans nmr-2 (20% identical), Drosophila melanogaster Nmdar2 (19% identical), Drosophila melanogaster clumsy (15% identical), and 36 more. Paralogues in human: GRIN3B (46% identical), GRIN2B (23% identical), GRIN2A (22% identical), GRIN2C (22% identical), GRIN2D (21% identical), GRIN1 (17% identical), GRIA2 (16% identical), GRIK1 (16% identical), GRIA3 (15% identical), GRIA4 (15% identical), GRIA1 (15% identical), GRIK5 (15% identical), and 5 more.
Diseases named in the same sentence as GRIN3A in open-access papers:
GRIN3A is named in the same sentence as 50 diseases in open-access papers, as found by Europe PMC text mining. Sharing a sentence is not in itself a finding about the gene and the disease. The quoted sentences say what the papers report.
schizophrenia (18 papers, 2012 to 2025). A major psychotic disorder characterized by abnormalities in the perception or expression of reality. "Genetic mutations or altered expression levels of GRIN3A in humans are implicated in cognitive deficits and diverse neurological/neuropsychiatric conditions such as schizophrenia, bipolar disorder, addiction, epilepsy, and Huntington's Disease 13,32–39." (PMID 41472680, 2025). "In our cohort, one of the GRIN3A variants, c.1438C>G, was also found to be associated with schizophrenia." (PMID 38075685, 2023). "Of note, variants among the GRIN3A are considered to be more relevant to autism spectrum disorders or schizophrenia, while GRIN1, GRIN2A, GRIN2B, and GRIN2D are more epilepsy-related." (PMID 38075685, 2023). "In humans, GRIN3A displays a distribution pattern highly similar to that of rodents, and alterations in GRIN3A expression or sequence are associated with several neuropsychiatric conditions such as schizophrenia, autism, epilepsy, and addiction (1, 63, –65)." (PMID 40924452, 2025). "Moreover, mutations or alterations in GRIN3A/Grin3a expression in humans and mice are linked to diverse neurological conditions such as schizophrenia, bipolar disorder, addiction, epilepsy, and Huntington’s disease making GluN3A an attractive candidate for therapeutic intervention 13,32–39." (PMID 41472680, 2025). "Among these, several schizophrenia-associated genes were also detected, including NTNG2, which is known to be involved in neurodevelopmental disorders and GRIN3A, a gene that encodes NMDA receptor subunits in neuronal nuclei." (PMID 38648100, 2024). "Disruptions in GRIN3A expression or function may lead to aberrant glutamate signaling, potentially contributing to the pathophysiology of various neurological disorders, including schizophrenia, autism spectrum disorder, and intellectual disability." (PMID 39396906, 2024).
epilepsy (8 papers, 2020 to 2025). A brain disorder characterized by episodes of abnormally increased neuronal discharge resulting in transient episodes of sensory or motor neurological dysfunction, or psychic dysfunction. "Thus, KA-induced epilepsy was followed by a decrease in GRIN3A, whereas MI treatment abolished this decrease." (PMID 41303586, 2025). "Thus, we selected GRIA1 and GRIN3A as those of the most upregulated and validated their change in expression in epilepsy by smFISH." (PMID 33028830, 2020). "Many of the selected genes have been found to be associated with neurological diseases, including autism [SHANK2], chronic pain [CACNG2], epilepsy [CHRNB2], Huntington’s disease [GRIN3A], and neurodegenerative diseases [SYBU]." (PMID 32848578, 2020).
autism (4 papers, 2017 to 2025). Persistent deficits in social interaction and communication and interaction as well as a markedly restricted repertoire of activity and interest as well as repetitive patterns of behavior. "They play an important role in dopamine-related processes, including addiction and attention (TRPC4), physiological and pathological processes in the central nervous system (GRIN3A), autism (NBEA), etc." (PMID 35205240, 2022).
nicotine dependence (4 papers, 2014 to 2021). Physical and psychological dependence on nicotine. "In a candidate gene study, both individual SNP and haplotype association tests of African-Americans and European-Americans revealed significant associations of Grin3A with nicotine dependence." (PMID 24465966, 2014). "Finally, based on previous data supporting an association of the glutamate receptor subunit gene, ionotropic N-methyl-d-aspartate 3A (GRIN3A), with nicotine dependence, 16 SNPs were examined in a Chinese Han population." (PMID 34512422, 2021).
melanoma (3 papers, 2014 to 2020). A malignant, usually aggressive tumor composed of atypical, neoplastic melanocytes. "Only the module turquoise had a significant enrichment (p = 0.009) of genes whose homologs displayed prognostic value in melanoma, such as Oca2, Samhd1, Nlrc5, Irf1, Ifitm3, Sp100, Dram1, Rtn1, Tcaf2, Parp10, and Grin3a." (PMID 32831131, 2020).
depression (2 papers, 2022). "The precise epigenetic regulation of GRIN3A is unknown, but DNA methylation in the promoter of glutamate ionotropic receptor NMDA type subunit 2a (GRIN2A), which is another subunit of NMDA, is strongly associated with major depressive disorder in humans." (PMID 35144563, 2022).
diabetes (2 papers, 2009 to 2021). "Along these lines, prolonged hyperglycemia was noted to significantly increase inhibitory Grin3a transcripts in Min6 β-cells, while a SNP in this gene has been associated with β-cell dysfunction and new onset diabetes following kidney transplantation." (PMID 33430405, 2021).
heroin addiction (2 papers, 2018 to 2021). "Our study identified variations in five candidate genes, including GRIN3A, GRIN3B, CYP2C19, TPH2, and COMT, contributing to susceptibility to heroin addiction." (PMID 33915886, 2021). "Regarding the variants in genes involved in the glutamatergic synapse, GRIN3A and GRM6 were two candidate genes related to heroin addiction and response to MMT, respectively." (PMID 30059533, 2018). "GRIN3A and GRIN3B may play roles in heroin addiction, acting as dominant-negative modulators of NMDA receptors." (PMID 33915886, 2021).
endothelial dysfunction (1 paper, 2013). In vascular diseases, endothelial dysfunction is a systemic pathological state of the endothelium (the inner lining of blood vessels) and can be broadly defined as an imbalance between vasodilating and vasoconstricting substances produced by (or acting on) the endothelium. "This is the first study to report that GRIN3A is a regulator of vascular inflammation and may be beneficial for many inflammatory diseases associated with endothelial dysfunction." (PMID 24278430, 2013).
Hyperammonemia (1 paper, 2018). An increased concentration of ammonia in the blood. "While Grin1a, Grin1b, Grin2da and Grin3a were hardly expressed at early developmental stages, their expression strongly increased at 5 dpf coinciding with the time point of hyperammonemia-induced neurotoxicity and mortality." (PMID 30199544, 2018).
Kawasaki disease (1 paper, 2013). A rare inflammatory disease characterized by an acute febrile, systemic, self-limiting, medium-vessel vasculitis primarily affecting children. "Association of GRIN3A genetic variants with CAA formation risk in Taiwanese Kawasaki disease by multivariate regression analysis." (PMID 24278430, 2013). "Effect of GRIN3A gene SNPs on the CAA formation in Taiwanese Kawasaki disease patients." (PMID 24278430, 2013).
osteonecrosis (1 paper, 2020). A none disease characterized by death of bone tissue due to a lack of blood supply. "A GWAS in children with ALL and osteonecrosis showed that the SNP rs10989692 near the glutamate receptor GRIN3A locus, was associated with osteonecrosis." (PMID 32848787, 2020).
tauopathy (1 paper, 2024). Neurodegenerative disorders involving deposition of abnormal tau protein isoforms (tau proteins) in neurons and glial cells in the brain. "Through comparison of multiple transcriptome datasets, followed by gene ontology analysis and protein–protein interaction mapping, we identified GRIN3A and GRM8 as the top two genes related to loss of postsynaptic function and tauopathy." (PMID 39396906, 2024). "In sum, by utilizing various databases (five transcriptome GEO datasets, STRING database, ToppGene database) and experimental validation model such as primary rat hippocampal neuron and iPSC‐derived human brain organoids, we identified a novel tauopathy biomarker GRIN3A in AD." (PMID 39396906, 2024). "Taken together, our results identified a novel tauopathy biomarker GRIN3A in AD." (PMID 39396906, 2024). "Interestingly, we identified that decreased NR3A (encoded by GRIN3A) and mGluR8 (encoded by GRM8) are correlated with tauopathy and loss of postsynaptic function in AD." (PMID 39396906, 2024).
cancer (4 papers, 2014 to 2024). A tumor composed of atypical neoplastic, often pleomorphic cells that invade other tissues. "Still, our comprehensive bioinformatics analysis of cancer–nerve crosstalk-associated genes in SKCM constructed a valuable prognostic model based on eight genes (GRIN3A, CCR2, CHRNA4, CSF1, NTN1, ADRB1, CHRNB4, and CHRNG) and common clinical characteristics." (PMID 37404751, 2023).
psychiatric disorder (4 papers, 2012 to 2023). A disorder characterized by behavioral and/or psychological abnormalities, often accompanied by physical symptoms. "The roles that GluN3A involved with cognitive function and various psychiatric diseases might make patients harboring variants in GRIN3A more susceptible to behavior ADR." (PMID 38075685, 2023).
tumor (4 papers, 2016 to 2024).
GRIN3A also shares sentences with these, for which no sentence is quoted: ischemia (5 papers); bipolar disorder (4); Huntington disease (4); neurological disorders (4); Alzheimer disease (3); Anxiety (3); glioma (3); autism spectrum disorder (2); brain ischemia (2); ischemic stroke (2); neurodegenerative disease (2); neurodevelopmental disorder (2); Obesity (2); prostate carcinoma (2); alcoholics (1); amyloid (1); brain disorder (1); brain infarct (1); cocaine addiction (1); cognitive decline (1); cognitive deficits (1); colitis (1); colon cancer (1); Coronary Artery Aneurysms (1); dementia (1); Hyperglycemia (1); infection (1); Intellectual disability (1); memory impairment (1); migraine with aura (1).
A further 4 diseases each share a sentence with GRIN3A in 1 paper.